MDM2 (MDM2 proto-oncogene)
Diseases named in the same sentence as MDM2 in open-access papers (continued):
Sharing a sentence is not in itself a finding about the gene and the disease.
ameloblastoma (3 papers, 2015 to 2024). The most common odontogenic tumor, arising from the epithelial component of the embryonic tooth and usually affecting the molar-ramus region of the mandible or maxilla. "MDM2 overexpression has been reported in ameloblastoma and hence linked to tumor progression." (PMID 27386018, 2015). "Other studies have reported more intense MDM2 expression in the peripheral cells of ameloblastoma and variation among the histopathological types, findings that were not confirmed in the present material." (PMID 38396916, 2024). "Seven of sixteen MDM2-positive ameloblastomas (43.75%) were BRAFV600E positive, two showed weak/ambiguous staining and were considered as negative, and seven were BRAFV600E negative." (PMID 38396916, 2024). "Ameloblastomas commonly express the human murine double minute 2 homologue (MDM2 or HDM2) protein." (PMID 38396916, 2024). "As for BRAFV600E-negative cases that overexpress MDM2, it should be noticed that MAPK-activating mutations other than BRAFV600E have been identified in ameloblastomas, and in some ameloblastomas the TGF-β pathway may be activated." (PMID 38396916, 2024). "The varying results on MDM2 immunoexpression among different studies may be attributed to technical parameters, but overall MDM2 expression was recorded in 181 of 226 ameloblastomas tested." (PMID 38396916, 2024). "Sixteen of forty-four (36.36%) cases of ameloblastoma showed MDM2 overexpression." (PMID 38396916, 2024). "Twenty-eight FFPE blocks of ameloblastoma cases from Nigerian patients were prepared for antibody processing to PTCH-1 (Polyclonal Anti-PTCH antibody ab39266) and MDM2 (Monoclonal Anti-MDM2 antibody (2A10) ab16895)." (PMID 27386018, 2015).
Autoimmunity (3 papers, 2017 to 2020). The occurrence of an immune reaction against the organism's own cells or tissues. "MDM2 can regulate a functional autologous immune response; therefore, it is linked to the development of autoimmunity." (PMID 31632275, 2019).
biliary tract cancer (3 papers, 2022 to 2025). "In a cohort of 34 patients with biliary tract cancer, actionable variants were detected in IDH1/2 (18%), followed by FGFR1/2 (16%), EGFR or ERBB2/3 (16%), PTEN (14%), MDM2 (10%), and PIK3CA (10%)." (PMID 36290850, 2022). "For example, PTEN, MDM2, and PIK3CA are not considered to be druggable markers for patients with biliary tract cancer under the latest knowledge." (PMID 36290850, 2022).
Cirrhosis (3 papers, 2002 to 2020). A chronic disorder of the liver in which liver tissue becomes scarred and is partially replaced by regenerative nodules and fibrotic tissue resulting in loss of liver function. "Sequencing of full-size mRNA revealed a MDM2 mis-sense mutation in an alcohol-induced cirrhosis." (PMID 11953887, 2002). "Moreover, this study provides a first clue to MDM2 splice variant analysis in cirrhosis of different origins." (PMID 11953887, 2002). "Overall, critical genes encoding for positive cell cycle progression factors (CCND1, CDK1, CDK2, E2F3, EIF4E, and MDM2) were found significantly up-regulated in HCV-cirrhosis with HCC." (PMID 22792259, 2012).
crescentic glomerulonephritis (3 papers, 2017 to 2019). A histopathologic term for a pattern of diseases characterized by extensive crescent formation in the glomeruli; patients present clinically with rapid deterioration of renal function, and possible progression to end-stage renal failure within weeks or months. "Since Nutlin3a (20 mg/kg); an MDM2 inhibitor, had been shown to ameliorated kidney injury by ischemia‐reperfusion 12 or crescentic glomerulonephritis, we anticipated that MDM2 inhibitors would also have some protective effects on cisplatin nephropathy." (PMID 30564368, 2019). "Moreover, MDM2 is involved in anti-GBM serum induced-crescentic glomerulonephritis by triggering the aberrant cell cycle entry of PECs and inflammatory cell infiltration." (PMID 28871126, 2017).
depression (3 papers, 2022 to 2024). "RNA editing modifications were analyzed using a panel of eight genes (CAMK1D, GAB2, IFNAR1, KCNJ15, LYN, MDM2, PDE8A, PRKCB) that we previously identified and whose editing combinations were suggested as biomarkers to distinguish BD from unipolar depression and subcategories of BD patients." (PMID 39684694, 2024).
embryonal rhabdomyosarcoma (3 papers, 2013 to 2023). A poorly circumscribed morphologic variant of rhabdomyosarcoma.
ependymoma (3 papers, 2015 to 2016). A WHO grade II, slow growing tumor of children and young adults, usually located intraventricularly. "The ependymoma cell lines were also treated with Nutlin-3, a small-molecule inhibitor of MDM2 with a similar mode of action to Actinomycin-D." (PMID 27556362, 2016).
Glucose intolerance (3 papers, 2016 to 2022). Glucose intolerance (GI) can be defined as dysglycemia that comprises both prediabetes and diabetes.
HCMV infection (3 papers, 2015 to 2023). "Reduced MDM2 expression during HCMV infection has been reported, and also shown here at 72 hpi." (PMID 27336364, 2016).
Hyperinsulinemia (3 papers, 2015 to 2023). An increased concentration of insulin in the blood. "Because hyperinsulinemia and IR are the crucial pathogenic signals for the development of NASH, in this study, we also found that insulin stimulation in vitro could lead to AKT, p-MDM2, MDM4 activation and impaired autophagy." (PMID 25826083, 2015).
Hypertension (3 papers, 2012 to 2025). The presence of chronic increased pressure in the systemic arterial system. "From these publications, we believe that MDM2 and IGN1 should be part of the apoptosis list, as well as REN and ADIPOQ should be part of the hypertension list." (PMID 23282288, 2012). "Taking the first and last genes in the list as examples, for each term (i.e., MDM2 and ING1 for apoptosis, and REN and ACE2 for hypertension), we found strong evidence in the most recent supporting publications for linking these non-gold standard genes to the query." (PMID 23282288, 2012).
intestinal cancer (3 papers, 2016 to 2020). "We constructed a proto-oncogene Mdm2 promoter-linked SEAP reporter plasmid (pMdm2-SEAP4.14h) that was used to stably transfect HCT-8 human intestinal cancer cells." (PMID 27119350, 2016).
ischemic stroke (3 papers, 2021 to 2025). A stroke disorder caused by obstruction of blood flow to the brain, due to thrombotic (local blood clot formation) or embolic (due to a blood clot or other material traveling from another site) event. "Moreover, KDM4A can increase MDM2 expression and reduce CTRP3 expression in microglia, thereby promoting polarization and exacerbating brain injury after ischemic stroke in mice." (PMID 40600192, 2025).
lipoblastoma (3 papers, 2024 to 2025). A lipoma usually occurring in the extremities of young children (usually boys). "Lipoblastomas are the most common adipocytic tumors in children, but if a tumor is located in the deep tissue or imaging findings are not typical, the possibility of ALT should be considered and immunohistochemistry for MDM2 and CDK4 should be added." (PMID 39109289, 2024). "A specimen was sent for cytogenetics and found to be negative for MDM2 and positive for FLAG1, ultimately revealing a diagnosis of lipoblastoma." (PMID 39011190, 2024).
lipodystrophy (3 papers, 2022). A congenital or acquired disorder characterized by abnormal loss or redistribution of the adipose tissue in the body. "Furthermore, adipocytes from old Adipo-MDM2-KO showed remarkable and progressive loss of SWAT, eWAT, and BAT, and leptin and adiponectin levels were nearly undetectable, revealing an early onset of lipodystrophy in this mice model." (PMID 36354755, 2022).
liver cirrhosis (3 papers, 2002 to 2020). "The prevalence of autoantibodies against MDM2 was significantly higher than that in liver cirrhosis (LC), chronic hepatitis (CH), and normal human sera (NHS)." (PMID 24955377, 2014). "The MDM2 mRNA levels of patients with HBV-related HCC were higher than those of patients with liver cirrhosis and chronic hepatitis B. The plasma levels of IL-6 and TNF-α were significantly higher in HBV-related HCC patients than that in liver cirrhosis and chronic hepatitis B patients." (PMID 33173438, 2020). "In liver cirrhosis, the affected hepatocytes may be more susceptible to tumorigenic stimuli leading to MDM2 overepression since MDM2 can no longer be bound by P14ARF and transported into the nuclei for inactivation." (PMID 11953887, 2002).
lymph node metastasis (3 papers, 2010 to 2021). "Previous studies detected MDM2 expression in tumor tissue and normal lung tissue in patients with NSCLC and found that MDM2 expression was related to tumor differentiation degree, clinical stage and lymph node metastasis." (PMID 33968713, 2021). "MDM2 expression levels were significantly higher in NPC patients with lymph node metastasis than in those without lymph node metastasis." (PMID 25435943, 2015). "Furthermore, MDM2 expression levels were significantly higher in NPC patients with lymph node metastasis than in those without lymph node metastasis (χ2, 16.361; P=0.001)." (PMID 25435943, 2015).
lymphopenia (3 papers, 2011 to 2021). Reduction in the number of lymphocytes.
male infertility (3 papers, 2018 to 2022). The inability of the male to effect fertilization of an ovum after a specified period of unprotected intercourse. "Only one case-control study by Haung and colleagues has investigated the association of MDM2 SNP 309 T>G with the risk of male infertility but our results do not support their research who reported a statistical association between MDM2 SNP 309 T>G with idiopathic male infertility." (PMID 30288482, 2018).
malignant peripheral nerve sheath tumor (3 papers, 2010 to 2024). Malignant peripheral nerve sheath tumor (MPNST) is a rare and often aggressive soft tissue sarcoma occurring in a wide range of anatomical sites. "Mixofibrosarcomas, malignant peripheral nerve sheath tumors, and undifferentiated sarcomas can also occasionally display MDM2 amplification." (PMID 38275873, 2024).
microcephaly (3 papers, 2017 to 2025). A congenital or acquired developmental disorder in which the circumference of the head is smaller than normal for the person's age and sex. "For example, variants in the splicing factor EFTUD2 that cause mandibulofacial dysostosis with microcephaly seem also to affect the splicing of MDM2." (PMID 41283296, 2025).